Y_RNA (Y RNA )
Gene: Miscellaneous RNA gene on chromosome 13 (28,629,794 to 28,629,883, forward strand). Ensembl gene ENSG00000273964.
Homologues: Orthologues: chimpanzee Y_RNA (97% identical), macaque Y_RNA (89% identical), pig Y_RNA (74% identical). Paralogues in human: Y_RNA (86% identical), RNY3 (84% identical), Y_RNA (84% identical), Y_RNA (83% identical), Y_RNA (82% identical), RNY3P16 (81% identical), RNY3P2 (81% identical), Y_RNA (81% identical), RNY3P1 (80% identical), Y_RNA (80% identical), RNY3P9 (79% identical), Y_RNA (79% identical), and 92 more.